ZNF554 (zinc finger protein 554)
Description:
May be involved in transcriptional regulation.
Synonyms: FLJ34817
Tractability: PROTAC: UniProt records ubiquitination sites on it; ubiquitination databases record sites on it.
Gene: Protein-coding gene on chromosome 19 (2,819,868 to 2,836,735, forward strand). Ensembl gene ENSG00000172006.
Subcellular location: Nucleus
Subcellular location (Human Protein Atlas): Nucleoplasm; Nucleoli
Pathways (Reactome):
Gene expression (Transcription): Generic Transcription Pathway
Gene Ontology:
Molecular function: protein binding; DNA-binding transcription factor activity, RNA polymerase II-specific; RNA polymerase II transcription regulatory region sequence-specific DNA binding
Biological process: regulation of transcription by RNA polymerase II; regulation of DNA-templated transcription
Cellular component: nucleolus; nucleoplasm; nucleus
Genetic constraint (gnomAD): Loss-of-function variants: 14 observed, 20.39 expected, observed/expected ratio (o/e) 0.69, 90% interval 0.45 to 1.07. The upper end of that interval is the gene's LOEUF score, 1.07, which puts it in group 4 of 6, group 1 being the genes least tolerant of losing a copy. Missense variants: 673 observed, 670.37 expected, observed/expected ratio (o/e) 1, 90% interval 0.94 to 1.07. Synonymous variants: 250 observed, 254.94 expected, observed/expected ratio (o/e) 0.98, 90% interval 0.88 to 1.09.
Homologues: Orthologues: chimpanzee ZNF554 (98% identical), macaque ZNF554 (87% identical), pig ZNF554 (67% identical), dog ZNF554 (61% identical), mouse Zfp78 (33% identical), Drosophila melanogaster CG3281 (25% identical), Drosophila melanogaster CG2712 (21% identical), Drosophila melanogaster Phs (19% identical). Paralogues in human: ZFP69B (36% identical), ZNF805 (36% identical), ZNF266 (36% identical), ZFP37 (35% identical), ZFP69 (35% identical), ZNF264 (35% identical), ZNF582 (35% identical), ZNF614 (35% identical), ZFP90 (35% identical), ZNF25 (34% identical), ZNF674 (34% identical), ZNF133 (34% identical), and 50 more.
Diseases named in the same sentence as ZNF554 in open-access papers:
ZNF554 is named in the same sentence as 10 diseases in open-access papers, as found by Europe PMC text mining. Sharing a sentence is not in itself a finding about the gene and the disease. The quoted sentences say what the papers report.
preeclampsia (2 papers, 2018 to 2020). Preeclampsia is a hypertensive disorder of pregnancy that is characterized by new-onset hypertension with proteinuria presenting after 20 weeks of gestation, and depending on mild or severe forms may initially present with severe headache, visual disturbances, and hyperreflexia. "Recently, we unveiled that ZNF554 regulates trophoblast invasion during placentation and its decreased expression leads to the early pathogenesis of preeclampsia." (PMID 32796700, 2020). "Among transcription regulatory genes of module M1, HLF had strong down-regulation only in preterm preeclampsia while ZNF554 was expressed at a lower level in all preeclampsia phenotypes." (PMID 30135684, 2018). "Of interest, ZNF554 immunostaining was faint in the syncytiotrophoblast in preeclampsia compared to controls." (PMID 30135684, 2018). "There were 9 genes (6 in the M2 and 3 in the M1 modules) dysregulated in BeWo cells, including FLT1, ARNT2, and ZNF554, similar to preeclampsia." (PMID 30135684, 2018). "Microarray analysis of ZNF554-silenced cells showed 185 DE genes including 18 DE placental genes in preeclampsia." (PMID 30135684, 2018). "Furthermore, our genome-wide transcriptomic analysis showed the emerging role of ZNF554 as a hub transcription factor that drives deep trophoblast invasion, and the pathogenesis of preeclampsia is partly originated from its dysregulation." (PMID 32796700, 2020). "In preterm preeclampsia, ZNF554 immunostaining of EVTs was weaker than in controls." (PMID 30135684, 2018). "Among hub genes of this module, ZNF554 was of most interest due to the biological processes enriched in its co-expression network, and also to its potential placenta- and preeclampsia-related regulation by transposable elements." (PMID 30135684, 2018). "Microarray analyses of ZNF554-silenced cells revealed 123 DE genes including 9 DE placental genes in preeclampsia, and the dysregulation of the “glycolysis/gluconeogenesis” pathway (OR = 7.8, q = 0.06) as well as 18 molecular functions including “RNA binding” (down) and “activin binding” (up)." (PMID 30135684, 2018). "Thus, the down-regulation of ZNF554 expression in the placenta of patients with preeclampsia may also be reflected in the DNA methylation of the transposable elements in its 5′ flanking region." (PMID 30135684, 2018).
astrocytoma (1 paper, 2020). "Furthermore, low ZNF554 expression was associated with shorter survival of grade III and IV astrocytoma patients." (PMID 32796700, 2020). "Immunohistochemistry (IHC) results showed that ZNF554 protein expression decreased with increasing tumor grades in patients with oligodendroglioma (ODG) and astrocytoma (AC)." (PMID 32796700, 2020).
endometrial cancer (1 paper, 2024). Primary or metastatic malignant neoplasm involving the endometrium (mucous membrane that lines the endometrial cavity). "ZNF554 inhibits the progression of endometrial cancer by regulating RBM5 and inactivating WNT/β-Catenin signaling pathway." (PMID 39717098, 2024).
glioblastoma (1 paper, 2020). The most malignant astrocytic tumor (WHO grade IV). "ZNF554 overexpression in U87 glioblastoma cells induced gene expression changes associated with cancer-and immune-related pathways, with the PI3K-Akt signaling pathway enriched most significantly." (PMID 32796700, 2020). "Genome-scale gene expression analysis identified dysregulation of 4.77% (899/18 834) of genes expressed in U87 glioblastoma cells overexpressing ZNF554." (PMID 32796700, 2020). "We also show that ZNF554 overexpression in U87 glioblastoma cells leads to dysregulation of several pathways and genes known to be impacted in adult diffuse gliomas." (PMID 32796700, 2020). "To reveal the impact of ZNF554 expression on glioblastoma cells, we transiently overexpressed ZNF554 in U87 glioblastoma cells." (PMID 32796700, 2020).
glioma (1 paper, 2020). A benign or malignant brain and spinal cord tumor that arises from glial cells (astrocytes, oligodendrocytes, ependymal cells). "Future studies should evaluate if low-grade gliomas lose ZNF554 as they undergo malignant transformation into high-grade gliomas." (PMID 32796700, 2020). "Congruently, cell proliferation was decreased and cell cycle was arrested in ZNF554-transfected glioma cells." (PMID 32796700, 2020). "Since ZNF proteins are immensely implicated in the development of several tumors including malignant tumors of the brain, here we explored the pathological role of ZNF554 in gliomas." (PMID 32796700, 2020). "Our in vitro studies suggest that enhanced expression of ZNF554 in such high-grade gliomas has the potential to suppress tumor growth and invasiveness." (PMID 32796700, 2020). "We found that the ZNF554 log2 expression level was lower in all glioma groups (ODG grade II: 7.673 ± 0.027, ODG grade III: 7.659 ± 0.030, AC grade II: 7.579 ± 0.029, AC grade III: 7.458 ± 0.027, GBM: 7.241 ± 0.035, p < 0.001 in all cases) compared to controls (8.272 ± 0.161)." (PMID 32796700, 2020). "Furthermore, the survival probability of patients with high ZNF554 expression was higher than those with low ZNF554 expression when all gliomas were analyzed together (p < 0.001)." (PMID 32796700, 2020). "While U87 cells used in our study are among the most commonly used glioma cell lines in neuro-oncology research, future studies could involve other glioma cell lines to test baseline expression of ZNF554 and its expression in overexpression/siRNA systems." (PMID 32796700, 2020). "We revealed decreased ZNF554 expression in adult diffuse gliomas with increasing tumor grade at both protein and mRNA levels, which possibly reflects its tumor suppressor nature in gliomas." (PMID 32796700, 2020). "Therefore, we analyzed ZNF554 mRNA expression in gliomas from the TCGA database." (PMID 32796700, 2020). "Since ZNF554 is a regulator of cell invasion, and it has high expression in the brain, our collaborative teams hypothesized that it may play a role in glioma development." (PMID 32796700, 2020). "Our results suggest that ZNF554 may be a novel prognostic biomarker for clinical patient management, especially in those with grade III and IV gliomas." (PMID 32796700, 2020).
malignant glioma (1 paper, 2020). A grade III or grade IV glioma arising from the central nervous system. "ZNF554 is a potential tumor suppressor, and its decreased expression may lead to the loss of oncogene suppression, activation of tumor pathways, and shorter survival in malignant glioma patients." (PMID 32796700, 2020).
oligodendroglioma (1 paper, 2020). A well-differentiated (WHO grade II), diffusely infiltrating neuroglial tumor, typically located in the cerebral hemispheres. "Although in vitro experiments were performed on an astrocytic glioma cell line, TCGA ZNF554 mRNA expression data indicate the importance of ZNF554 in the pathophysiology of oligodendrogliomas as well." (PMID 32796700, 2020).
tumor (3 papers, 2020 to 2023). "Upregulation of ZNF554 is a potential tumor suppressor and its decreased expression may lead to the loss of oncogene suppression, activation of tumor pathways, and shorter survival of patients with malignant glioma." (PMID 37013470, 2023). "In contrast, ZNF554 is regarded as a potential tumor suppressor in malignant gliomas, and its reduced expression may lead to the loss of oncogene suppression and the activation of tumor pathways." (PMID 35927248, 2022). "Thus, the potential promotion of its expression by gene therapy to restore ZNF554’s tumor suppressor effect may provide therapeutic advantages and improve patient outcomes in adult diffuse gliomas." (PMID 32796700, 2020).
ZNF554 also shares sentences with these, for which no sentence is quoted: cancer (1 paper); malignant tumors of the brain (1).